ADAM10 (ADAM metallopeptidase domain 10)
Diseases named in the same sentence as ADAM10 in open-access papers (continued):
Sharing a sentence is not in itself a finding about the gene and the disease.
cancer (continued). "Our future will screen more small molecules by molecular docking simulations and/or experimental validation for inhibiting ADAM10 expression and investigating the resulting mechanism, such as DNA/RNA G-quadruplex modification, that may develop a potential therapeutic strategy for anti-cancer." (PMID 39211038, 2024). "There are indications that high concentrations of sPD-L1, together with high expression of ADAM10 (ADAM Metallopeptidase Domain 10) and ADAM17 (ADAM Metallopeptidase Domain 17) acted as predictors of poor response to immunotherapy in cancer patients." (PMID 37816808, 2023). "Previous findings with other ADAMs have shown that both ADAM10 and ADAM17 are regulated by RT and subsequently affect the cancer response to ionizing radiation." (PMID 37495855, 2023). "Because the ADAM‐10 SNP can affect the clinical course of some cancers and the OSCC owns correlation to the ADAM‐10 expression." (PMID 36946281, 2023). "Although Notch signalling is not regulated through increasing the activity of ADAM10 but instead depends on ligand‐dependent exposure of the Notch cleavage site, increased ADAM10‐mediated shedding of other cell surface molecules has been implicated in multiple cancers." (PMID 37165578, 2023). "Using this platform, they found the specific combinations of biomarkers for cancer diagnosis (MMP-9, ADAM-10, and ADAM-17) with joint entropy and programming." (PMID 36831937, 2023). "For example, the molecular targets of ADAM10 and ADAM17 in inflammation and cancer are tumor necrosis factor-alfa (TNF alfa), inteleukin-6 (IL-6), ICAM-1 and epidermal growth factor (EGF)." (PMID 37185715, 2023). "We focused on ADAM10 because it was found to be significantly upregulated in LRC and is known to play an important role in the progression of T-ALL and cancers of multiple entities, as well as in normal hematopoiesis." (PMID 37422628, 2023). "A disintegrin and metalloproteinase domain-containing protein 10 (ADAM10), -17, and -19 are upregulated in H. pylori-infected individuals, and ADAM9, -12, -15, and -20 are deregulated in cancer biopsies." (PMID 35269560, 2022). "Thus, for the first time, differences in the levels of 20S proteasomes, ADAM10+/ADAM17-, MMP9+ and MMP9+/MMP2+/EMMPRIN+ in plasma exosomes subpopulations between CPPs and CRCPs were revealed, thereby indicating the feasibility of using them to predict cancer risk." (PMID 33773551, 2021). "This cancer is treated by targeting HER2 with the antibody Herceptin, but one resistance mechanism to the therapy appears to be upregulation of ADAM10 and its cleavage and removal of HER2." (PMID 34201472, 2021). "Aderbasib (INCB007839), is a selective inhibitor of ADAM10 and ADAM17, which is currently in clinical trials for cancer treatment." (PMID 33684175, 2021). "For these reasons, ADAM10 and ADAM17 have been proposed as biomarkers and possible targets of therapy in cancer." (PMID 34067041, 2021). "This is intriguing because ADAM10 and ADAM17 have recently been shown to cleave PD-L1 from the surface of cancer cells." (PMID 33672843, 2021). "Among them, ADAM10 cleaves MICA, MICB, and ULBP-2 in different types of cancer cells and its increased expression correlates with cancer progression in MM, malignant pleural mesothelioma, oral squamous cell carcinoma, and gastric cancer." (PMID 32570952, 2020). "Several members of ADAMs, such as ADAM10, ADAM12, and ADAM15, have been reported to be overexpressed in human cancers." (PMID 32637415, 2020). "Another mechanism behind the reduction in the amount of mCX3CL1 on a cancer cell is an increase in the expression of ADAM10 and TACE/ADAM17, enzymes releasing sCX3CL1, which results in a reduction in mCX3CL1 on a cancer cell." (PMID 32466280, 2020). "Of interest, ADAM10 was detected on platelet surface and contributed to NKG2D ligand cleavage from cancer cells." (PMID 32269567, 2020). "HER ligands can also be released by ADAMs (ADAM10 and ADAM12) to promote cancer cell growth, migration, and invasion." (PMID 32637415, 2020).
cancer (continued). "Among them ADAM10, a catalytically active member of the ADAM family of proteases, is involved in the cleavage of MICA, MICB, and ULBP-2 molecules in various types of cancer cells." (PMID 32269567, 2020). "We subsequently proved that pharmacological restoration of membrane-bound MICA in HCC cells boosted natural killer cell-mediated anti-cancer effects, confirming that a MICA sheddase, a disintegrin and metalloproteinase 10 (ADAM10), is a therapeutic target." (PMID 29721164, 2018). "Considering the importance of ADAM-10, ADAM-17, and ADAM-28 in cancer progression, we detected their expression in HC by immunohistochemistry." (PMID 29776401, 2018). "In particular, ADAM10 and ADAM17 appear to promote cancer progression by releasing HER/EGFR ligands." (PMID 30081852, 2018). "By sharing several substrates with ADAM10, inhibition of ADAM17 is also effective in different kinds of cancer and inflammatory disorders." (PMID 28066176, 2016). "Among the predicted targets of miR-122, ADAM10, IGF1R, and CCNG1 play key roles in tumorigenesis and drug sensitivity in various cancers." (PMID 26514126, 2015). "ADAM10, a member of the ADAM family, has been found to be upregulated in many cancers, including ovarian, colon and prostate cancers." (PMID 24548763, 2014). "The overexpression of ADAM8, ADAM9, ADAM10, ADAM12, ADAM15, ADAM17, and ADAM28 are reported from various cancers." (PMID 22272227, 2012). "Here, we demonstrate that both cancer and HIV-infected cells shuttle activated TACE and ADAM10 into microvesicles in order to induce TNFa secretion by an autocrine and paracrine mechanism." (PMID 26082068, 2012). "L1CAM-mediated cancer progression can be induced by proteolytic cleavage-products of full-length L1CAM (L1CAM-FL) by family members of a disintegrin and metalloproteinase (ADAM) such as ADAM10 and ADAM17." (PMID 38263290, 2024). "In the fight against cancer, blocking NTF generation by targeting ADAM10 proteolytic activity could be a relevant therapeutic strategy." (PMID 38667323, 2024). "Specifically, ADAM10 regulates constitutive LAG3 cleavage, while ADAM17 regulates LAG3 cleavage induced by T cell receptor signaling, where ADAM17 showed immune and SARS-CoV-2 entry for the expression in patients with cancer." (PMID 39211038, 2024). "IDO could also catalyze tryptophan to kynurenine in cancer cells, decreasing the expression of NKG2D ligands on the surface of cancer cells by ADAM10, and this reduced expression of NKG2D ligands inhibited degranulation and IFNγ release by NK cells." (PMID 38022646, 2023). "As in other cancer cells, ectodomain shedding of L1CAM is mediated by ADAM10 and ADAM17, we investigated the expression of the soluble L1CAM ectodomain in cell culture supernatant after ADAM10/17 single and double knockdown." (PMID 36293469, 2022). "Even though ADAM10 and respective inhibitors are highly discussed as novel targets for cancer treatment, ADAM10 has not been very much investigated in combination with radiotherapy." (PMID 34055644, 2021). "Currently, ADAM-10 and ADAM-17 present the strongest bodies of evidence for involvement in cancer." (PMID 33802262, 2021). "FasL can be cleaved by metalloproteinases such as MMP-7, ADAM10, and MMP-3 in various cell types and under various conditions, such as osteoblast apoptosis, T-cell activation, and the acquisition of chemoresistance by cancer cells." (PMID 32053892, 2020). "Herein, we will review advances on the protease-mediated cleavage of NKG2D ligands in response to chemotherapy-induced stress focusing on: (i) the role played by ADAM10 in this process and (ii) the implications of NKG2D ligand shedding in the course of cancer therapy and in senescent cells." (PMID 32269567, 2020).
cancer (continued). "A disintegrin and metalloproteinase 10 (ADAM10), a catalytically active member of the ADAM family of proteases, is involved in the cleavage of some NKG2D ligands in various types of cancer cells either in steady state conditions and in response to an ample variety of stress stimuli." (PMID 32269567, 2020). "Indeed, transient RNAi-mediated silencing of ADAM10 or ADAM17, or both, in distinct cancer cell lines revealed a considerable heterogeneity with regards their role in the proteolytic cleavage of MICA and MICB." (PMID 32269567, 2020). "Effect of stress conditions on ADAM10 and NKG2D ligand shedding in cancer models." (PMID 32269567, 2020). "Therefore, the ADAMs, particularly ADAM-10 and ADAM-17, have been described as the most prominent sheddases, being widely expressed and commonly over-expressed in cancer cells and involved in cleaving diverse substrates." (PMID 32948029, 2020). "Interestingly, beyond the role of ADAM10 in the NKG2D ligand proteolytic cleavage, this protease has also been described to affect the shedding of other molecules involved in the anti-cancer immune response." (PMID 32269567, 2020). "Furthermore, MICA and MICB shedding from a range of tumour cell lines was attributed to either or both ADAM10 and ADAM17, but the regulation of this process was different depending on the cancer cell lines tested." (PMID 33352921, 2020). "C-X3-C motif chemokine ligand 1 (CX3CL1)/fractalkine is a chemokine released after cleavage by two metalloproteases, ADAM metallopeptidase domain 10 (ADAM10) and ADAM metallopeptidase domain 17 (ADAM17), involved in inflammation and angiogenesis in the cancer microenvironment." (PMID 30845779, 2019). "ADAM10 and ADAM17 are even discussed as potential targets for cancer therapy." (PMID 30081852, 2018). "ADAM10 is also known to promote cell growth in HCC and other cancers." (PMID 29721164, 2018). "Our results suggest that therapies against ADAM10 and ADAM17 may promote cancer stem cell migration away from the tumourigenic niche resulting in a differentiated phenotype that is more susceptible to treatment." (PMID 27541285, 2017). "ADAM10 is reported as a sheddase that can cleave transmembrane proteins such as amyloid precursor protein (APP), E-cadherin, N-cadherin, CD44 and Notch, all of which play a significant role in proliferation, migration, invasion or stemness of cancer cells." (PMID 27259866, 2016). "Furthermore, a number of selective ADAM inhibitors, especially against ADAM10 and ADAM17, have been shown to have anti-cancer effects." (PMID 21906355, 2011). "ADAMs shown to play a role in cancer include ADAM9, ADAM10, ADAM12, ADAM15 and ADAM17." (PMID 21906355, 2011). "Besides a different ratio of premature and mature ADAM10 between the cancer cell lines, no obvious differences in PrP or ADAM10 levels were observed in cell lysates upon treatments." (PMID 38980441, 2024). "ADAM10 is the major source of human epidermal growth factor receptor 2 (HER2) ectodomain shedding activity in HER2-overexpressing breast cancer cells, and is known to promote cancer cell migration, invasiveness and metastasis in several contexts of cancer progression, as well as in brain glioma." (PMID 32098349, 2020). "This could be the reason for not including ADAM10 agonists in cancer clinical trials, although its use in other conditions such as Alzheimer's disease." (PMID 32328365, 2020).
cancer (continued). "More generally, this suggests that similar intramembrane proteolysis possibly occurring in other membrane proteases, such as ADAM10, and their not-yet-identified intracellular functions should be considered when their proteolytic activities are targeted in cancer treatment." (PMID 32493324, 2020). "Interestingly, our statistical analysis showed statistically nonsignificant trend of increased ADAM-10 immunoexpression in cancer cells from the primary tumor and the presence of distant metastasis (P = 0.088)." (PMID 26266086, 2015). "However, knockdown of miR-494 in CD44−ALDH1−non-HNC-TICs enhanced cancer stemness and oncogenicity, while co-knockdown of Bmi1 and ADAM10 effectively reversed these phenomena." (PMID 26090866, 2015). "However, it has been found ADAM10 in the nucleus of cancer but not in normal prostate cells, suggesting a role of this particular localization in disease progression." (PMID 25053185, 2014). "Investigating whether androgen-induced ADAM10 upregulation shifts APP processing toward sAPPα production and how this affects cancer biology will be critical for determining whether targeting and enhancing ADAM10 could serve as a therapeutic strategy for cancer." (PMID 41614805, 2025). "However, the use of ADAM10 for cancer cell targeting has not been undertaken yet." (PMID 38399697, 2024). "Previous studies mostly focussed on ADAM10’s role in extracellular matrix degradation for angiogenesis and metastasis or on its processing of cellular substrates regulating differentiation and cancer cell survival, yet did not consider or reveal any link to PrP." (PMID 35084572, 2023). "Moreover, soluble E-cadherin in serum serves as cancer prognostic marker and the soluble fragment in urine corresponds to the 80 kDa ectodermal fragment of the protein, which can be cleaved by several proteases including plasmin, MMP3, MMP7, ADAM10, and ADAM-15." (PMID 32121033, 2020). "Moreover, the interactions between ADAM10 and MET could influence how these proteins are sorted into EVs, thereby impacting intercellular communication and the spread of signaling molecules in physiological and pathological processes, including cancer metastasis." (PMID 39769452, 2024). "The non-cancerous bile ducts showed negative or weak staining for ADAM-10, ADAM-17, and ADAM-28, whereas most cancer cells showed strong staining for these three proteins." (PMID 29776401, 2018).
infection (32 papers, 2011 to 2026). The state of being infected such as from the introduction of a foreign agent such as serum, vaccine, antigenic substance or organism. "In mice, ADAM10 inhibitors prevent the loss epithelial integrity that is typically induced by S. aureus Hla during infections of the skin and lung." (PMID 27043625, 2016). "Consequently, it is believed that activation of ADAM10 by Hla is important for S. aureus ability to penetrate epithelial and endothelial barriers and thus cause invasive infection." (PMID 27043625, 2016). "In summary, co-depletion of LEDGF, ADAM10 and Nup153 replicated the effects, in terms of modulation of susceptibility to infection and viral DNA detection, observed through increased levels of miR-155 both in the context of TLR3 stimulation and ectopic expression in primary human MDMs." (PMID 23028330, 2012). "The role of ADAM10 in the development of severe S. aureus infection has been highlighted in studies where the conditional disruption of ADAM10 or its inhibition with GI254023X have shown development of milder local infections in lung and skin of mouse models." (PMID 41408425, 2026). "Reduced ADAM10 and ADAM17 surface expression upon infection and inflammatory stimulation, respectively, are linked to their release in exosomes, which was reduced by Ca2+ chelation." (PMID 39497138, 2024). "Within 4 hours of infection, WT mice developed increased vWF deposition compared with VE-Cad ADAM10–/– mice preceding the difference in platelet aggregation seen at 6–8 hours." (PMID 37788087, 2023). "Serum IL-10 was increased in WT mice 8 hours after infection, whereas VE-Cad ADAM10–/– mice had a minimal increase in IL-10 levels, mirroring the response seen in humans who survive infection." (PMID 37788087, 2023). "Serratia-infection-induced Ca2+ influx can trigger ADAM10 activation, thereby leading to E-cadherin shedding." (PMID 38069398, 2023). "WT mice developed more substantial platelet aggregates than did VE-Cad ADAM10–/– mice 6–8 hours after infection." (PMID 37788087, 2023). "In vivo imaging of VE-Cad ADAM10–/– mice infected with P. aeruginosa or S. pneumoniae revealed significantly reduced areas of platelet aggregation in the liver 6–8 hours after infection compared with control WT mice." (PMID 37788087, 2023). "In the present study, we observed a different extent of ADAM10 contribution to transepithelial migration in response to infection with P. aeruginosa and stimulation with ExoA, respectively." (PMID 35163191, 2022). "Both findings suggest that epithelial ADAM10 is regulated in a pathogen-specific manner during infection." (PMID 35163191, 2022). "Most importantly, infection with P. aeruginosa resulted in the release of ADAM10 on exosomes, mediating proteolytic cleavage in trans (on distinct cells)." (PMID 35163191, 2022). "As obvious, ADAM10 functions during different phases of infection and has to be tightly regulated via disease-specific mechanisms, which have to be taken into account when thinking about ADAM10 based treatment strategies." (PMID 33392273, 2020). "One crucial substrate of ADAM10, indicated by the lethality of ADAM10 knockout mice, is Notch which has divergent immune modulatory functions in infection." (PMID 33392273, 2020). "Cre infection strongly reduced levels of immature and mature ADAM10 levels in the neuronal cell lysate." (PMID 26802628, 2016). "Regarding infectivity, silencing of LEDGF decreased infection to a greater extent than silencing of ADAM10 or Nup153." (PMID 23028330, 2012). "Silencing ADAM10 expression with small interfering RNA (siRNA) 48 hours before infection significantly inhibited HIV-1 replication in primary human monocyte-derived macrophages and in CD4+ cell lines." (PMID 21569301, 2011). "Moreover, it provides evidence supporting the inhibition of ADAM10 as a potential therapeutic target for preserving endothelial function during invasive infection." (PMID 41408425, 2026).